CD4 (CD4 molecule)
Diseases named in the same sentence as CD4 in open-access papers (continued):
Sharing a sentence is not in itself a finding about the gene and the disease.
tumor (continued). "Finally, after reaching the tumor and transfecting cells, there was a substantial increase in the number of lymphocytes, NK, CD8+, and CD4+ activated cells, which in turn led to a significant decrease in tumor growth rate and an increase in mice survival." (PMID 31662751, 2019). "Similarly, PD-1, a negative regulator of adaptive anti-tumor immunity, was increased in lymph node and splenic CD8+ T cells and splenic CD4+ of metastatic Stat4−/− mice compared to tumor bearing WT mice." (PMID 32010142, 2019). "For instance, clinical infusion of EGFRvIII-directed CAR-T cells for the treatment of glioblastoma resulted in influx of CD4+CD25+FoxP3+ cells in the tumor, whereas CD19-targeted CAR-T cells against B-cell lymphoma and leukemia did not increase the frequency of Treg cells." (PMID 31058083, 2019). "Having observed that PD-L1-specific G1 HTLs have ability to kill tumor cells, we further evaluated whether PD-L1241-265-specific CD4+ T-cells exhibit an antitumor effect in vivo setting using an immunodeficient mouse." (PMID 31221178, 2019). "However, the number of CD4+ T cells also increased in tumor after HMGN1/R848 or TheraVac treatment, which raises a possibility to cause immunosuppression by CD4+ T regulatory cells." (PMID 30696484, 2019). "This correlated with an increased tumor CD4+ T-lymphocyte infiltration." (PMID 31849934, 2019). "However, NF-κB also plays a major role in CD4+ Treg (T regulatory cells) activation, an immunosuppressive T cell population that supports tumor immune evasion and disease progression." (PMID 31394796, 2019). "Notably, DOX’s effect on the tumor-infiltrating CD4+ and CD8+ T cells was of a similar pattern to Nano-DOX but with a lesser magnitude." (PMID 31623629, 2019). "Furthermore, ruxolitinib elevated numbers of tumor infiltrating CD4+IL17A+ Th17 and CD4+Foxp3+ regulatory T cells." (PMID 31407334, 2019). "Conversely, the efficacy of tumor-infiltrating CD4+ T cells may be controversial, which might be explained by the different CD4+ subtypes." (PMID 31443339, 2019). "Although cytotoxic CD8+ T cells have been the focus of eliciting an anti-tumor response, it is clear that this response benefits from CD4+ T cell help and it has been shown that cross-priming of CD8+ T cells by DCs requires CD4+ T cell help for effective cytotoxic CD8+ T cell responses." (PMID 31379821, 2019). "However, tumor escape by upregulation of PD-1 is frequent and additional treatment with anti-PD-1 antibody restored effector functions of CD4+ and CD8+ T cells as well as of NK cells and γδT cells." (PMID 31555582, 2019). "IgG class specific antibodies indicate participating of CD4 T cells in anti-tumor immune response." (PMID 31717542, 2019). "Moreover, Th1 and Th17 subtypes contribute to the upregulation of peripheral CD4+CXCR5+ T-cells in patients with metastasis or high tumor grade." (PMID 31354634, 2019). "This work highlights the importance of CD4+ T cells in tumor immunology." (PMID 31362778, 2019). "However, PD-1 expresses on CD4+ T cells, γδ T cells and tumor associated macrophages (TAMs) in addition to CD8+ T cells, mediating extensive immunosuppression in tumor microenvironment (TEM)." (PMID 31138162, 2019). "Additionally, an analysis of the correlation network reconstructed using TCGA-SKCM emphasized KMO and KYNU with high variability among BRAF wild-type compared with V600E, which underscored their role in distinct CD4+ T-cell behavior in tumour immunity." (PMID 31434983, 2019). "Thus, this dual function of stimulatory and regulatory effects of IFNγ on anti-tumor immunity can be exploited by vaccine-activated CD4+ T cells." (PMID 30956760, 2019). "Th1 and Th2 cells, two of the most common CD4+ subtypes, are generally modulated in tumours." (PMID 31409774, 2019). "(D) CD4+ T cell numbers per gram of tumor in different groups (top)." (PMID 31511064, 2019). "Hypoxic tumors recruit CD4+ Tregs to suppress effector T cell function and promote tumor tolerance." (PMID 30626396, 2019).
tumor (continued). "Interestingly, CD4+ T cell depletion alone in chemerin-expressing tumors resulted in improved tumor growth suppression." (PMID 31139180, 2019). "rMVA and rMVA-CD40L immunization changed the phenotype of tumor-infiltrating CD4+ and CD8+ T cells." (PMID 31695037, 2019). "Furthermore, we clarified which cytotoxic immune cell make the most significant contribution to the effects of the RPS3-based DC vaccine on tumor prevention using depletion with antibodies against CD4, CD8, and NK." (PMID 30819254, 2019). "Taken together, these results suggested that the effect of YPF inhibited tumor growth might depend on CD4+ T cells and macrophages in tumor microenvironment." (PMID 31780946, 2019). "The frequency of tumor-infiltrating B cells was markedly reduced upon CD4+ T cell depletion." (PMID 31300052, 2019). "The question of whether these cytokines can promote CD4+CTL activity or be involved in the inhibition of tumor angiogenesis, remains to be explored." (PMID 31366386, 2019). "Th17 cells also might be a source of tumor-induced FoxP3+ cells besides nTreg and iTreg cells which have developed from naïve CD4+ precursors." (PMID 31024835, 2019). "One key objective of our study was to compare the transcriptome of CD4+ T cells responding to tumors, whether in the tumor itself or in draining lymphoid organs, to that of cells responding to infection." (PMID 31801070, 2019). "As the artesunate concentration increased, the percentage of the Th1/CD4+ T cells in the peripheral CD4+ T cells rose in a dose-dependent manner, and the Th1/CD4+ T proportion in the tumor-infiltrating lymphocytes was elevated along with the artesunate concentration." (PMID 31038546, 2019). "Moreover, we introduce the first NY-BR-1-specific H2b-restricted CTL epitope and describe the composition of tumor infiltrating immune cell populations with particular focus on NY-BR-1-specific CD4+ T cells and HLA-DR4 positive tumor-associated macrophages." (PMID 31519152, 2019). "CD4+ T cells could destroy tumor cells through cytolytic mechanisms or modulate tumor microenvironment to exert their anti-cancer role." (PMID 31297335, 2019). "Splenic CD4+ T cells of tumor bearing Stat4−/− mice produced less IL-17 compared to WT mice." (PMID 32010142, 2019). "For example, CXCL9 and CXCL10 induce effector Th1/Th17 cells and CXCL11 drives a Treg and Th2-biased effector cell polarization upon activation of CXCR3 on CD4+ T cells, while they upregulate tumor cell-related proteins that are beneficial for their survival, such as PD-L1." (PMID 31216755, 2019). "Collectively, tumor-derived cDC2s are likely to contribute to CD4 T cell activation in the dLN." (PMID 31143179, 2019). "Treg cells, another subset of CD4+ T cells, play an important role in tumour immunosuppression." (PMID 31409774, 2019). "Considering the higher expression of chemokines, including CCR5 and CCR6, which might attract EpCAM+ CD4+ T cells to the tumor sites, we determine whether EpCAM+ CD4+ T cells are present in the tumor microenvironment within CC patients using light microscopy." (PMID 31354723, 2019). "Moreover, resveratrol was shown to have inhibitory effects on CD4+/CD25+ cell population among CD4+ cells through reduction of FoxP3, a specific regulatory T cell marker in tumor-bearing C57BL/6 mice." (PMID 30791624, 2019). "In mice carrying MM tumors, p-Tvax increased tumor infiltration of CD4+ T cells." (PMID 31428586, 2019). "Given that tumor‐infiltrating T cells are the main antitumor response effectors, by the infiltration of CD4+ and CD8+ T cells and depletion of Treg cells to reverse the immunosuppression may explain the synergistic efficacy of the CPMV+CPA combination therapy." (PMID 31453050, 2019). "Therefore, over regulation of IL-10 production by tumor cells promotes tumor progression through the escape of immunosurveillance performed by NK, CD4, and CD8 lymphocytes." (PMID 31737570, 2019).
tumor (continued). "Thus, to obtain a broad representation of antigen-specific TILs, not limited to GP-specific cells, we used PD-1 expression as a surrogate for tumor antigen specificity and purified tumor CD4+CD44hiPD-1+ T cells (PD-1hi TIL) for scRNA-seq." (PMID 31801070, 2019). "Interestingly, patient-derived tumor infiltrating DNT cells expressed a lower level of PD-1 than conventional CD4+ and CD8+ T cells." (PMID 30857561, 2019). "Both tumor-bearing macrophages and cryo-thermal macrophages could directly inhibit CD4+ T-cell proliferation." (PMID 30833570, 2019). "Immunohistochemistry showed that all tumors had an activated tumor immune microenvironment positive for nuclear NF-κB/p65RelA, CD4, and CD8 T cell markers, but only four out of eight tumors were positive for the PD-1 immune checkpoint molecule, which is indicative of an exhausted immune environment." (PMID 31618954, 2019). "While CD8+ T-cells are considered a central driver of the anti-tumor activity of the immune response, recent reports suggest that the adoptive transfer of CD4+ T-cells can lead to tumor cytotoxicity and clinical response, both in animal models and in patient studies." (PMID 31118084, 2019). "In patients who did not receive neoadjuvant chemotherapy, overall survival is positively influenced by the combination of high tumor gC1qR expression and high CD4 T-cell infiltration, and negatively impacted by the combination of high gC1qR expression and high Ki-67 index." (PMID 31681580, 2019). "Notably, this treatment fosters tumor-reactive CD8+ and CD4+ T cell presence in tumors and tumor-draining LNs (tdLN), limiting tumor progression of three different mouse cancer models, of which two do not express exogenous or dominant Ags." (PMID 30961656, 2019). "In addition to the importance of CD8+ T cells, multiple studies have highlighted the importance of CD4+ T cells in tumor rejection." (PMID 31998317, 2019). "Although our 19305DP-TCR-transduced CD4+ T cells showed moderate cytotoxicity, it is possible that production of anti-tumor effector cytokines such as IFN-γ and TNF-α from CD4+ T cells may damage cancer cells." (PMID 30626427, 2019). "Preclinical murine tumor models of mammary carcinoma have demonstrated tumor regression with aOX40 + aPD‐1 dual treatment, with efficacy likely dependent on augmentation to CD4+ T‐cell helper functions, enhancing CD8+ T‐cell cross‐priming and recruitment to TDLNs." (PMID 31485330, 2019). "Although the presence of CD4 Treg cells within the tumor microenvironment has been described as a potential driver of tumor immune escape, peripheral frequencies of this subset may not be sufficiently reflective of local conditions." (PMID 31176366, 2019). "However, recent evidence shows that CD4+ T cells also exert anti-tumor efficacy and CD4+ T cells have already been part of the TCR infusion product used in early clinical trials." (PMID 30470934, 2019). "Moreover, we demonstrate that adoptive transfer of tumor antigen specific CD4+ Th1 cells into tumor bearing C57BL/6 mice results in accumulation of TAMs with a M1 shifted phenotype and enhanced M1-associated gene expression." (PMID 30853959, 2019). "Responders were associated with higher CD8+ cells but lower CD4+ cells infiltration, lower Foxp3 + Treg density and higher CD8+ to Treg ratio (responder vs non-responder), indicating strongly enhanced T effector function within the tumours." (PMID 30587849, 2019). "Other tumor-supportive CD4+ T-cell subsets are also reported to be expanded in CLL." (PMID 31484424, 2019). "However, IR also led to an increased number of tumor-infiltrating FoxP3+CD4+ Tregs, and consequently a significantly decreased ratio of CD8+ T/Tregs in the irradiated tumors (p < 0.05, Student’s T test)." (PMID 31704921, 2019).
tumor (continued). "In one of our experiments testing TR-CD4-cell response in a DP*04+ patient with exceptionally high-titer spontaneous anti-NY-ESO-1 serum antibody (reciprocal titers: > 10,000,000), we established a DP*04-binding NY-ESO-1157-170 peptide-specific CD4+ T-cell line and tested direct tumor recognition." (PMID 30626427, 2019). "Strikingly, tumor reactive cytotoxic CD4+ T cells could be induced following checkpoint blockade therapy." (PMID 31379821, 2019). "In addition, tumor-infiltrating lymphocytes contained highly activated CD4+ and CD8+ T cells, indicating the tumors provided an immunogenic environment." (PMID 31775882, 2019). "This led us to conclude that vaccination with CIITA-tumor cells affected also a crucial component of the regulatory circuit, the Tregs, by preventing their increase in number in the tumor microenvironment and in so doing facilitating the triggering and persistence of anti-tumor CD4+ TH cells." (PMID 31417570, 2019). "Th1-cytokines derived from CD4 lymphocytes have a role in preventing tumor progression." (PMID 31534952, 2019). "It is likely that PD-L1 blockade in these cells may enhance their antigen presentation capacities, and together with memory CD4 T cells trigger strong anti-tumor activities." (PMID 30986912, 2019). "CD4+ T cell depletion—as in our model—resulted in significantly reduced tumor growth, hypothesized to be due to a reduction in immunosuppressive regulatory CD4+ T cells." (PMID 31139180, 2019). "Indeed, ILT2 and ILT4 expression has been observed in tumor-infiltrating immune cells such as CD4+ and CD8+ T cells." (PMID 31134067, 2019). "Interestingly, the culture of E.G7 cancer cells in the RCCS for 72 h resulted in an apparent disruption of tumor evasion function as JAWS II DC were able to promote IL-2 production by the CD4+ T cells." (PMID 31602007, 2019). "Our results also showed that tumour infiltrating CD4+ and CD8+ T cells isolated 3 weeks after TC-1 tumour inoculation secrete less IFNγ compared with those isolated at 3 weeks, whether or not the T cells express PD-1." (PMID 31277636, 2019). "Breg cells could down‐regulate biologic activities of effector CD4+ T cells and promote tumour growth with the characteristic phenotype of CD19+ Tim+." (PMID 30467955, 2019). "Besides improving the efficacy of tumor-reactive CD8+T cells, the CD4+T cells have been recognized with a CTL activity in both tumor models and human anti-tumor responses." (PMID 31366386, 2019). "Thus, there is great therapeutic potential in harnessing the power of memory CD4+ T cells to promote the most effective anti-tumor immune responses." (PMID 31379821, 2019). "Moreover, the effect of tumor-bearing macrophages on inhibiting proliferation of CD4+ T cells was much stronger than that of cryo-thermal-induced M1 macrophages." (PMID 30833570, 2019). "Lessons learnt on the importance of MHC class II-restricted CD4 T cell responses in autoimmune pathogenesis may shed light on this question in anti-tumor responses as well, since the anti-tumor response is essentially a self-specific response." (PMID 31143179, 2019). "Thus, we co-cultured PD-L1241-265-specific CD4+ T-cells with the HLA-DR-matched tumor cell lines expressing PD-L1." (PMID 31221178, 2019). "Moreover, low concentration of IL-24 promoted FoxP3 mRNA expression in tumor-infiltrating CD4+ T cells (Tukey test, P = 0.012)." (PMID 31921658, 2019). "While treatment with β-lap alone or β-lap combined with CD4+ T cell depletion controlled MC38 tumor growth, CD8+ T cells depletion abolished β-lap’s antitumor effect, suggesting that CD8+ T cells, but not CD4+ T cells, are required for β-lap-mediated tumor regression." (PMID 31324798, 2019).
tumor (continued). "Furthermore, the heterogeneous CD4+ T cell response corresponds with the diverse TCR repertoire and is indicative of a polyclonal CD4+ T cell response to multiple tumor antigens." (PMID 30956760, 2019). "Interestingly, CD4+ T cells were long-lived effector cells able to secrete IFN-γ (Th1) or IL-4 (Th2) after challenge with MHC-II-positive tumor cells." (PMID 31156634, 2019). "Our observations indicate that selecting tumor antigen-specific TCR genes from CD4+CD8+ double-positive T cells could be an alternative strategy for discovering high-affinity tumor antigen-specific TCR genes." (PMID 30626427, 2019). "Detailed analyses of adoptively transferred CD4+ T cells during tumor challenge revealed the expression of granzyme B, FasL, TNF-α, and IFN-γ in such T cells that might be involved in the antitumour activity." (PMID 31183361, 2019). "CD4 were clearly stained in the cell membranes of tumor-infiltrating cells." (PMID 31852159, 2019). "Thus, active STAT3 in CD4+ T cells generates an inflammatory environment around the budding tumor aids its growth by stimulating angiogenesis and abrogates antitumor response." (PMID 31861720, 2019). "In addition, tumor-infiltrating lymphocytes, in breast cancer, comprise CD4+ T cells specific for class II restricted tumor antigens." (PMID 31771178, 2019). "In addition, lymphocytes play important roles in tumour immunity; for example, CD8+ cytotoxic T-cells damage tumour cells, whereas CD4+Foxp3+ regulatory T-cells suppress the function of these cells." (PMID 31462002, 2019). "Moreover, in the blood, the percentages of CD4+ or CD8+ T cells were also inversely associated with the PD‐L1 expression level, which is the same as what was observed in the tumours." (PMID 30714229, 2019). "Additionally, deficiencies in Treg TRAF6 expression lead to reduced FOXP3+ T‐cell frequencies within the CD4+ T cells infiltrating several lymphoid and tumor tissues." (PMID 30886050, 2019). "However, to the best of our knowledge, the role of CD4+ helper T cells in facilitating and mediating anti-tumor immune responses in combination with checkpoint blockade has not been studied." (PMID 31475002, 2019). "Mice depleted of CD4+ T cells prior to tumor challenge were unable to clear the tumor." (PMID 31112530, 2019). "It was suggested that Foxp3+CD4+ T cells might in fact help to prevent or delay inflammation-mediated tumour development, as supported by the presence of remarkably higher levels of anti-inflammatory IL-10 from the serum samples of NSCLC patient." (PMID 30944831, 2019). "Extract 1 should be employed carefully, and further tested, to estimate whether the increase of the regulatory helper CD4+cell level is counterbalanced with the tumor-suppressing mechanisms in vivo." (PMID 31949880, 2019). "The heightened tumor immunity in STAT6-deficient mice is likely not due to the balance between CD4+, Th1, and Th2 cells, which is consistent with the results from other studies." (PMID 31798581, 2019). "Domatinostat increased the expression of MHC-II on both tumor and immune cells, which is beneficial for CD4+ T cell priming in principle; however, interactions with the LAG3 receptor could subvert the CD4+ T cell response against the tumor." (PMID 31703604, 2019). "The increased levels of Foxp3+ and CD4+ cells along with enhanced mRNA expression levels of Foxp3 in the laparotomy group strongly indicate that laparotomy can result in an increase in Tregs population in tumor tissue." (PMID 30216450, 2019). "IL-10 and TGF-β reduce synthesis of interferon-gamma (IFN-γ) and TNF-α by pro-inflammatory CD4 T cells, thus, lower tumor-specific cytotoxicity of CD8 cells, inhibit the main functions of dendritic cells and NK cells and this way induce tolerance to tumor cells." (PMID 31717542, 2019).